GINS4 (GINS complex subunit 4)
Diseases named in the same sentence as GINS4 in open-access papers (continued):
Sharing a sentence is not in itself a finding about the gene and the disease.
tumor (continued). "Here, we show that GINS4/SLD5 is recurrently upregulated across human cancers at transcript and protein levels and marks tumor programs enriched for DNA replication, chromosome segregation, and mitotic control." (PMID 42182163, 2026). "Next, we found that the GINS4 expressing cells formed larger and more abundant tumor spheres that the control cells in both PC9 and H358 cells through tumor sphere assays (both ** P < 0.01)." (PMID 31253190, 2019). "Consistent with the ONCOMINE analysis, all four GINS genes were up-regulated in tumor samples of HCC from TCGA database with 6.382, 3.789, 2.442, and 2.770-fold elevation for GINS1, GINS2, GINS3, and GINS4 mRNA expressions, respectively (P<0.001 for all)." (PMID 30413605, 2018). "In vivo experiments indicate that the absence of GINS4 can suppress tumor growth in HCC, increase the expression of GPX4, and decrease the levels of Ki67, while also reducing the activity of the POLE2/PI3K/AKT signaling pathway." (PMID 40386780, 2025). "Specifically, GINS4 expression was significantly greater in HCC patients that belong to age ≤60 years old (P = 0.011), female (P = 0.010), AFP level >400 (P = 0.007), with residual tumor (P = 0.009), relapse (P = 0.017)." (PMID 33842367, 2021). "Finally, GINS4 was positive correlated with tumor purity (r = 0.148, p = 2.06e-02), and negative correlated with the levels of tumor-infiltrating CD4+ T cell (r = −0.175, p = 6.57e-03)." (PMID 36092720, 2022). "Additionally, the AUC value for the capacity of GINS4 expression level to differentiate HCC samples at TNM I, II, and III stage from adjacent tumor tissues was 0.835 (95% CI = 0.796–0.896), 0.878 (95% CI = 0.822–0.937), and 0.906 (95% CI = 0.840–0.946), respectively." (PMID 33842367, 2021).
cancer (16 papers, 2013 to 2026). A tumor composed of atypical neoplastic, often pleomorphic cells that invade other tissues. "Furthermore, the IPA results indicated that GINS4 is implicated in cancer cell proliferation, cell cycle, apoptosis and metastasis through Rac1 and CDC42 and their downstream signaling pathways: MAPK/ERK pathway, PI3K/AKT pathway and PTEN pathway." (PMID 31754397, 2019). "Our findings identify SLD5/GINS4 as a regulator of dynein-dependent centrosome maturation and a candidate vulnerability in replication-driven cancers, with potential value for biomarker-guided therapeutic stratification." (PMID 42182163, 2026). "We conducted GSEA analysis base on CGGA RNA-seq and TCGA RNA-seq data and found that GINS4 was significantly enriched in the Notch signaling pathway, pathway in cancer, and JAK-STAT pathway." (PMID 34556022, 2021). "Accumulating evidence has demonstrated that GINS4 acts as an oncogene to promote the tumorigenesis of various cancer." (PMID 34556022, 2021). "GINS4 as well as other GINS family members have the potential to regulate cancer cell proliferation, suggesting their use as therapeutic targets for cancer treatment." (PMID 31253190, 2019). "SLD5, encoded by GINS4, is a core component of the GINS replication complex and is frequently elevated in tumors, but whether it links replication-associated cancer states to centrosome control has remained unclear." (PMID 42182163, 2026). "Furthermore, our study also found that GINS4 was correlated with immune cell infiltration not only in ESCC but also in many other cancers." (PMID 35365175, 2022). "We also performed a pan-cancer analysis to investigate the role of GINS4 in other cancers." (PMID 35365175, 2022). "Thus, GINS4 exerts a vital effect on the malignant progression of tumors and potentially serves as a valuable target for cancer therapy and diagnosis." (PMID 33842367, 2021). "Moreover, GINS4 knockdown inhibited cancer progression in H1299 cells, serving as evidence that knocking down GINS4 inhibits cancer progression in vivo." (PMID 34616505, 2021). "A growing body of evidence now suggests that GINS4 is a key to the development of cancer." (PMID 34556022, 2021). "However, only one published study has reported the biological functions of GINS4 in human cancers." (PMID 31754397, 2019). "Our study suggested that GINS4 was correlated with prognosis and immune cell infiltration level of ESCC and other cancers." (PMID 35365175, 2022). "Thus, further interventions should focus on how to convert GINS4 into GINS5 with better prognosis and sensitivity to immunotherapy, such as adoptive T-cell immunotherapy, cancer vaccine, and reprogramming the microenvironment." (PMID 36345721, 2022). "GINS4, an indispensable component of the GINS complex, is vital for a variety of cancer." (PMID 34556022, 2021). "Our study found that GINS4 might be a novel biomarker correlated with the prognosis not only in ESCC but also in many other cancers." (PMID 35365175, 2022). "Finally, pan-cancer analysis revealed that GINS4 might be a novel immune-related prognostic gene in ESCC and other cancers." (PMID 35365175, 2022). "In conclusion, GINS4 might be a novel immune-related prognostic gene in ESCC and other cancers." (PMID 35365175, 2022).
infection (2 papers, 2021). The state of being infected such as from the introduction of a foreign agent such as serum, vaccine, antigenic substance or organism. "Additionally, the upregulation of GINS4 was associated with poor prognosis of HCC, especially in age >60 years old, histological grade G1, HBV-negative infection, and with recurrence subgroups, suggesting that GINS4 was a potentially independent risk factor affecting OS in HCC patients." (PMID 33842367, 2021).
GINS4 also shares sentences with these, for which no sentence is quoted: breast carcinoma (5 papers); non-small cell lung carcinoma (3); esophageal squamous cell carcinoma (2); melanoma (2); acute myeloid leukemia (1); adrenocortical carcinoma (1); cholangiocarcinoma (1); chondrosarcoma (1); colon cancer (1); esophageal cancer (1); Ewing sarcoma (1); liver fibrosis (1); lung squamous cell carcinoma (1); mesothelioma (1); osteosarcoma (1); pancreatic adenocarcinoma (1); pancreatic cancer (1); pancreatic ductal adenocarcinoma (1); paraganglioma (1); pheochromocytoma (1); primary immunodeficiency (1); thymoma (1); thyroid carcinoma (1); transitional cell carcinoma (1); viral infection (1).